RN7SL785P (RNA, 7SL, cytoplasmic 785, pseudogene)
Gene: Miscellaneous RNA gene on chromosome X (47,280,811 to 47,281,063, reverse strand). Ensembl gene ENSG00000266158.
Homologues: Orthologues: chimpanzee Metazoa_SRP (99% identical), macaque Metazoa_SRP (41% identical), macaque Metazoa_SRP (40% identical). Paralogues in human: RN7SL391P (71% identical), RN7SL96P (70% identical), RN7SL460P (69% identical), Metazoa_SRP (69% identical), Metazoa_SRP (68% identical), RN7SL510P (68% identical), RN7SL596P (68% identical), Metazoa_SRP (67% identical), RN7SL274P (66% identical), RN7SL371P (66% identical), Metazoa_SRP (66% identical), RN7SL470P (66% identical), and 701 more.